RNU6-189P (RNA, U6 small nuclear 189, pseudogene)
Gene: Small nuclear RNA gene on chromosome 14 (49,901,850 to 49,901,950, reverse strand). Ensembl gene ENSG00000251929.
Homologues: Orthologues: chimpanzee U6 (100% identical), mouse Gm24851 (84% identical), pig U6 (78% identical). Paralogues in human: RNU6-1331P (94% identical), RNU6-242P (94% identical), RNU6-379P (93% identical), RNU6-727P (93% identical), RNU6-1011P (92% identical), RNU6-1274P (92% identical), RNU6-43P (92% identical), RNU6-558P (92% identical), RNU6-66P (92% identical), RNU6-1060P (91% identical), RNU6-1094P (91% identical), RNU6-1131P (91% identical), and 1288 more.